PPARG (peroxisome proliferator activated receptor gamma)
Diseases named in the same sentence as PPARG in open-access papers (continued):
Sharing a sentence is not in itself a finding about the gene and the disease.
Insulin resistance (continued). "Lobeglitazone (Lobe) is a novel thiazolidinedione antidiabetic drug that reduces insulin resistance by activating peroxisome proliferator-activated receptor-gamma (PPARγ)." (PMID 29979770, 2018). "It has also been reported that in advanced pregnancy, PPARγ declines, thus accelerating adipose tissue insulin resistance and facilitating lipolysis in the subcutaneous adipose tissue of obese pregnant women with GDM." (PMID 30037087, 2018). "Phosphorylation as a mechanism of action of PPARγ agonists has been recently suggested linking its role to obesity, inflammation, and insulin resistance." (PMID 30420872, 2018). "We hope safer PPARγ agonists or modulators with excellent efficacy and fewer adverse effects will be available for treating metabolic diseases and insulin resistance in the near future." (PMID 30079233, 2018). "As such, pharmacological activation of PPARγ has emerged as an efficient approach for treating metabolic disorders with the current use of thiazolidinediones to improve insulin resistance in diabetic patients." (PMID 29883404, 2018). "In short, the physiological impact and role of diminished PPARγ expression in insulin resistance during the aging process are not clearly understood." (PMID 29747466, 2018). "Defective signaling though PPARγ plays an important role in adipose tissue insulin resistance and, the use of thiazolidinediones can greatly improve this phenotype." (PMID 29678181, 2018). "Rosiglitazone, a PPARγ agonist, improved neuronal insulin resistance in high fat diet rat model by increasing the phosphorylation of AKT/PKB at Ser473." (PMID 30420872, 2018). "Thiazolidinediones (TZD) work to decrease insulin resistance by binding to peroxisomeproliferator-activated receptors gamma (PPARγ)." (PMID 28514939, 2018). "Given the synergistic effect of hypoxia and insulin resistance in liver fibrosis, previous study showed that hypoxia leads to a decrease in PPARγ expression, followed by inhibition of IR transcription, resulting in the blockade of IGF-1 and subsequent signals." (PMID 29686697, 2018). "PPARγ is still one of the most important targets for the treatment of insulin resistance and diabetes mellitus, even though current use of TZDs in clinical practice is limited because of undesirable adverse effects." (PMID 30079233, 2018). "Nevertheless, PPARγ is still one of the most important targets for the treatment of insulin resistance and diabetes mellitus, and novel strategies to modulate PPARγ activity to enhance its beneficial effects and reduce unwanted adverse effects are anticipated." (PMID 30079233, 2018). "The overexpression of PPARγ in the mouse skeletal muscle also increased adiponectin expression, which protected these mice from high-fat diet induced insulin resistance." (PMID 29747466, 2018). "Taken together, the results show that inhibition of the MEK/ERK pathway improves insulin resistance not only by down‐regulating PPARγ phosphorylation, but also through PPARγ‐independent reduction of inflammatory cytokine secretion by adipocytes and monocytes." (PMID 29160030, 2018). "Targeting adipose tissue and in particular specific functions of PPARg is a promising approach for the treatment of insulin resistance and type 2 diabetes but requires better understanding of the in vivo regulation of PPARg responses." (PMID 29973382, 2018). "Activated PPARγ delayed the progress of DKD by improving insulin resistance, lowering blood pressure, ameliorating inflammation, reversing cell cycle arrest, increasing adiponectin, improving oxidative stress, and other mechanisms." (PMID 29849705, 2018). "Butanol extract of WP of A. indicum reduces insulin resistance in rodents by peroxisome proliferator activated receptor-gamma (PPAR-γ) agonist activity and enhancing glucose utilization." (PMID 29057840, 2017). "PPARγ is also thought to improve carbohydrate and lipid metabolism and thereby block the development of insulin resistance in diabetic or obese mice." (PMID 28900399, 2017).
Insulin resistance (continued). "It was reported that flavonoids and polyphenolic compounds can suppress insulin resistance, possibly mediated via activation of PPARγ, reduced oxidative stress, and enhanced glucose uptake and insulin sensitivity." (PMID 28529969, 2017). "First, we investigated the association between cognitive aging and three insulin resistance-related genes, namely the ADAMTS9, GCKR, and PPARG genes." (PMID 28225792, 2017). "In liver-specific PPARγ-deficient mice, the development of HFD-induced NAFLD and insulin resistance was suppressed." (PMID 28578672, 2017). "Previous studies have demonstrated that PPARγ and aP2 play an important role in lipid metabolism, insulin resistance, hyperglycemia, and atherosclerosis." (PMID 29441115, 2017). "For the development of diabetes, PPARγ gets phosphorylated by CDK5 at serine 273 leading to alterations in many genes in the adipose tissue resulting in increased insulin resistance." (PMID 28243251, 2017). "Rosiglitazone, a PPARγ agonist, has been reported to enhance the insulin sensitivity of cells and tissues, alleviate insulin resistance, and exert a protective effect on nerve cells." (PMID 28790390, 2017). "Studies performed at the cellular level showed that PPARγ activation directly modulated the expression or phosphorylation of specific molecules of insulin signaling cascade to ameliorate insulin resistance." (PMID 28690544, 2017). "Targeted deletion of PPARγ in adipose tissue had been found to result in lipodystrophy or no visible adipose tissue, dyslipidaemia and adipokine deregulation, and extreme insulin resistance." (PMID 28611668, 2017). "Thiazolidinediones (TZDs, glitazones) activate peroxisome proliferator-activated receptor gamma (PPARγ) which decreases insulin resistance." (PMID 28280846, 2017). "TZD, a PPARγ agonist, has been reported to decrease the blood glucose levels and ameliorate insulin resistance in diabetic animal model and patients and has been widely used in clinical practice." (PMID 28690544, 2017). "Naturally occurring mutations within the PPARG coding sequence can lead to PPARG loss-of-function (LOF), severe lipodystrophy, insulin resistance, and diabetes in humans." (PMID 28588550, 2017). "Adipose-specific activation of PPARγ is sufficient to reverse whole body insulin resistance to a similar degree as systemic TZD treatment." (PMID 28690544, 2017). "PPARγ activation by rosiglitazone is widely used to overcome insulin resistance to treat type 2 diabetic patients." (PMID 28831172, 2017). "The results of our in vitro studies showed that compounds 3a and 3f not only exhibited strong effects on insulin resistance but also weakened toxicity on cells compared with the full PPARγ agonist pioglitazone." (PMID 27853282, 2016). "Present study demonstrates that LFE and its active component FSB act as selective PPARγ antagonists and reduce body weights and hepatic steatosis, and improve insulin resistance in ob/ob mice and KKAy mice." (PMID 27176632, 2016). "In adipose tissue, PPARG deletion leads to increases in bone mass, lipoatrophy, and insulin resistance (IR)." (PMID 27579030, 2016). "In particular, PPARγ plays an important role in controlling adipose tissue inflammation and insulin resistance through the activation and infiltration of alternatively activated (M2) macrophages." (PMID 27379017, 2016). "PPARγ plays an important role in the modulation of adipocyte hypertrophy and insulin resistance after exposure to a high-fat diet." (PMID 27806128, 2016). "Possible medications to treat or manage T2DM include oral hypoglycemic agents, such as sulfonylureas; a third class of agent that binds to PPARG to reduce insulin resistance; and a fourth class that acts on the intestinal absorption of glucose." (PMID 27376154, 2016). "Mice with selective deletion of PPARγ in hepatocytes developed relative fat intolerance, increased adiposity, hyperlipidemia, and insulin resistance." (PMID 28115925, 2016).
Insulin resistance (continued). "Liver-specific ablation of PPARγ in mice leads to increased adiposity and insulin resistance, but these mice respond to TZD treatment." (PMID 27483259, 2016). "15d-PGJ2 is the endogenous ligand of PPARγ and can regulate metabolism of adipose tissue and restrain insulin resistance." (PMID 27069916, 2016). "Macrophage secretes various cytokine and it leads to insulin resistance through decreasing the phosphorylation of IR and PPARγ." (PMID 28053990, 2016). "Meanwhile, GW9662 or PPARγ siRNA treatment significantly attenuated APL- induced insulin resistance improvement as evidenced by decrease of glucose uptake capability in palmitate -treated L6 myotubes." (PMID 27391974, 2016). "Isorhamnetin reduced body weight, ameliorated insulin resistance and alleviated hepatic steatosis in obese mice via the suppression of PPARγ transactivity." (PMID 26775807, 2016). "Another insulin resistance index was measured by levels of PPARγ and phospho-PPARγ, an important transcription factor improving the insulin resistance in the fat tissues." (PMID 28053990, 2016). "Mice heterozygous for PPARγ showed increased insulin sensitivity instead of the expected insulin resistance." (PMID 27483259, 2016). "These reinforce the pivotal role of PPARγ in the liver regulating lipid homeostasis and protecting other organs from lipotoxicity and insulin resistance." (PMID 27483259, 2016). "Overall, these results demonstrate the preventive role of curcumin on diet induced insulin resistant in rats by ameliorating the altered levels of metabolic changes and potential binding of curcumin with PPARγ as agonist in the treatment of insulin resistance." (PMID 27777867, 2016). "Peroxisome proliferator-activated receptor γ (PPARγ) is recognized as a key regulator of insulin resistance." (PMID 27853282, 2016). "In contrast with the severe insulin resistance in P467L PPARγ patients, the P465L PPARγ mutant mice have normal insulin sensitivity." (PMID 27483259, 2016). "Phosphorylation of PPARγ at Ser273 by cyclin-dependent kinase 5 (Cdk5) can affect the expression of distinct PPARγ target genes increasing insulin resistance in mouse models." (PMID 27483259, 2016). "In conclusion, our results demonstrate that LFE and FSB both inhibit PPARγ-stimulated adipocyte differentiation via PPARγ antagonism, and have beneficial effects on body weight, insulin resistance, and hepatic steatosis in ob/ob and KKAy mice." (PMID 27176632, 2016). "Few examples include PPARG mutation in familial partial lipodystrophy (FPLD3), INSR in Donahue syndrome and Type A insulin resistance, HNF4A in Maturity-Onset Diabetes of Young (MODY1), and INS in Diabetes-type hyperglycemia and hyperinsulinemia." (PMID 27376154, 2016). "In the present study, isorhamnetin significantly ameliorated the insulin resistance, fatty liver, hyperlipidemia and other metabolic disorders as other PPARγ antagonist did." (PMID 26775807, 2016). "Since SIRT1, by direct deacetylation of PPARγ, recruits the BAT program coactivator Prdm16 to PPARγ, it also plays a crucial role in the induction of genes typical for BAT and repression of visceral WAT genes associated with insulin resistance." (PMID 27104517, 2016). "Loss-of-function mutation V290M in the ligand-binding domain of the peroxisome proliferator activated receptor γ (PPARγ) is associated with a ligand resistance syndrome (PLRS), characterized by partial lipodystrophy and severe insulin resistance." (PMID 27761505, 2016). "Here, we present in vivo and ex vivo data providing evidence that increased circulating levels of insulin trigger fatty liver development and insulin resistance by stimulating hepatic expression of the FA transporter Cd36 in a Pparγ-dependent manner." (PMID 26085100, 2015). "Here, we report for the first time that EPO treatment enhances hepatic AKT pathway activity to improve insulin resistance via a PPARγ-dependent mechanism." (PMID 26643367, 2015).
Insulin resistance (continued). "Pharmacological activation of PPARγ improves insulin resistance in diabetes and decreases steatosis in NAFLD patients by restoring adipose tissue insulin sensitivity and adiponectin release." (PMID 26273621, 2015). "In contrast, elevated resistin has been proposed to increase insulin resistance, and the repression of resistin expression in normal mice by PPARγ agonists is thought to enhance insulin sensitivity." (PMID 25951943, 2015). "Future clear mechanism dissection of how these 2 receptors interact would resolve the puzzles why TR4 and PPARG have those opposite roles in different diseases including insulin resistance, atherosclerosis, osteoporosis, and now PCa." (PMID 25859557, 2015). "Our findings are the first to demonstrate that EPO improves hepatic insulin resistance via PPARγ-dependent AKT activation." (PMID 26643367, 2015). "In summary, we show that increased intake of sucrose in CBA mice results in rapid development of hyperinsulinemia, hepatosteatosis, and insulin resistance and that insulin enhances hepatic expression of the FA transporter Cd36 in a Pparγ-dependent manner." (PMID 26085100, 2015). "TZDs improve insulin resistance by activating peroxisome proliferator-activated receptor gamma (PPARγ) and ameliorate diabetic and other nephropathies, at least, in experimental animals." (PMID 26074951, 2015). "Recently Spiegelman and colleagues proposed that TZDs inhibit the phosphorylation of PPARγ at Ser273 by cyclin-dependent kinase (Cdk) 5, thus preventing the development of insulin resistance." (PMID 26074951, 2015). "PPARγ agonists, such as the thiazolidinediones (e.g. rosiglitazone), can reverse insulin resistance in adipocytes (20, –, 24)." (PMID 26240143, 2015). "Decreased expression of PPARγ mRNA has been reported in liver biopsies of HIV-infected subjects with insulin resistance and unexplained liver enzyme elevation 6, suggesting an effect of HIV on liver PPARγ expression." (PMID 26735218, 2015). "Thiazolidinediones (TZDs) are a class of oral anti-diabetic medication that improves insulin resistance by acting as a selective agonist of the peroxisome proliferator activated receptor gamma (PPARγ)." (PMID 25875942, 2015). "Our results revealed that EPO/EPOR upregulates PPARγ expression to alleviate insulin resistance in hepatocytes." (PMID 26643367, 2015). "To study this, we used the TNFα model of insulin resistance in 3T3-L1 adipocytes, which has been reported to be reversed by treatment with the PPARγ agonist pioglitazone." (PMID 26240143, 2015). "In summary, this study confirmed that chronic treatment with pioglitazone, a PPARγ agonist, not only ameliorates systematic insulin resistance and decreases plasma TG but also exacerbates hepatic steatosis and liver lesions in obese diabetic KKAy mice." (PMID 24799887, 2014). "The peroxisome proliferator-activated receptor gamma (PPARG) and the insulin receptor substrate (IRS1) genes have been shown to be associated with both insulin resistance and type 2 diabetes." (PMID 24447396, 2014). "PPARγ agonists, such as thiazolidinediones, are used as therapeutic agents in T2D treatments, reversing the insulin resistance in target tissues." (PMID 24427296, 2014). "We suggest that hyperinsulinemia in Mat-Ob offspring, driven by peripheral insulin resistance, promotes the transcriptional upregulation of hepatic genes, including PPARγ, to promote de novo lipogenesis in the liver." (PMID 24789994, 2014). "We investigated the independent and joint effects of PPARG Pro12Ala and IRS1 Gly972Arg on markers of insulin resistance and T2DM in an African population with elevated risk of T2DM." (PMID 24447396, 2014). "In rodent disease models, PPARγ agonists prevent increased adiposity and body weight, and improve insulin resistance and dyslipidemia." (PMID 25280587, 2014). "The optimal dose of GJ aqueous extract of 200 mg/kg exerts a PPARγ-activating hypoglycemic effect and improves insulin resistance in SIIR rats." (PMID 24438349, 2014).
Insulin resistance (continued). "SirT1-dependent deacetylation of Lys268 and Lys293 is required to recruit the BAT program co-activator Prdm16 to Pparγ, leading to selective induction of BAT genes and repression of visceral WAT genes associated with insulin resistance." (PMID 25514854, 2014). "Hepatic insulin resistance is also coupled to enhanced liver PPARγ levels that function to increase lipid synthesis." (PMID 25937836, 2014). "PPARγ is a component of the thrifty genotype supposedly increasing a person's inclination towards insulin resistance." (PMID 25258478, 2014). "Muscle-specific PPARγ knockout mice exhibit an increase in adiposity and develop insulin resistance, but are still responsive to TZDs." (PMID 24690289, 2014). "PPAR-gamma (PPARγ) is the primary target of the drug class of thiazolidinediones (TZDs), which are used to treat diabetes mellitus and other diseases featuring insulin resistance." (PMID 24498211, 2014). "For instance, they are able to act as activators of peroxisome proliferator activated receptor gamma (PPARγ); which stimulates the differentiation of preadipocytes to adipocytes, generating an increase in insulin receptors, thus reducing insulin resistance." (PMID 24741627, 2014). "PPARγ knockout mice presented several alterations with opposite results: some studies showed a reduced fat formation, and protection against obesity and insulin resistance with lipodystrophy." (PMID 25566082, 2014). "Recent reports show that pharmacological activation of a second KDT501 target, AGTR2, in combination with PPARγ activation, ameliorates insulin resistance and reverses β-cell damage in diabetic pancreatic tissue in T2D mice." (PMID 24498211, 2014). "Extensive literature exists on the beneficial effects of synthetic PPARγ agonists, and in particular pioglitazone, in limiting insulin resistance, protecting pancreatic β cell function and our own data suggest a protective effect on nephropathy." (PMID 23533381, 2013). "Thiazolidinediones (TZDs), agonists of PPARγ, stimulated gene expression and increased the plasma level of adiponectin in obese mice and obese people with insulin resistance." (PMID 23342006, 2013). "Otherwise, downstream of IL-4 receptor α (IL-4Rα) is the nuclear hormone receptor peroxisome proliferator-activated receptor γ (PPARγ), and when activated, it inhibits the expression of genes that promote inflammation and protects against insulin resistance." (PMID 23894289, 2013). "Pioglitazone improves peripheral insulin resistance by activating peroxisome proliferator-activated receptor-gamma (PPARγ)." (PMID 23606892, 2013). "Researchers have established that one of the ways to combat insulin resistance and diabetes therapeutically is to tackle the covalent modifications of PPARγ, though more extensive studies need to be done." (PMID 24324517, 2013). "It is generally accepted that by binding and activating PPARγ, TZDs repartition fatty acids (FAs) to adipose tissue and away from muscles, liver, and circulation, thus improving insulin resistance." (PMID 23150725, 2012). "Although the TZD-type PPARγ agonists improve insulin resistance with remarkable efficacy in hyperglycemia, their effects on the associated dyslipidemia are limited." (PMID 23150725, 2012). "Thiazolidinediones are characterized by their ability to decrease insulin resistance by specifically targeting at PPARγ to mediate its activity and have been suggested to slow down the progression of insulin resistance." (PMID 23213321, 2012). "Normally, PPARγ is expressed at very low levels in the liver, but its expression is dramatically increased in animal model with insulin resistance and hepatic steatosis such as db/db mice." (PMID 23145054, 2012). "In free-fatty-acid-induced insulin resistance muscle cells, berberine improves insulin resistance and improves glucose uptake by decreasing PPARγ and FAT/CD36 protein expression." (PMID 23213296, 2012).